NBPF4 (NBPF member 4)
Synonyms: FLJ32833
Tractability: No criterion of Open Targets' tractability assessment is met for any kind of drug.
Gene: Protein-coding gene on chromosome 1 (108,222,464 to 108,244,081, reverse strand). Ensembl gene ENSG00000196427.
Subcellular location: Cytoplasm
Subcellular location (Human Protein Atlas): Cytosol; Nucleoplasm
Gene Ontology:
Cellular component: cytoplasm
Genetic constraint (gnomAD): Loss-of-function variants: 9 observed, 8.51 expected, observed/expected ratio (o/e) 1.06, 90% interval 0.63 to 1.75. That is too few expected variants to judge how well the gene tolerates losing a copy. Missense variants: 79 observed, 123.09 expected, observed/expected ratio (o/e) 0.64, 90% interval 0.53 to 0.77. Synonymous variants: 41 observed, 48.67 expected, observed/expected ratio (o/e) 0.84, 90% interval 0.65 to 1.09.
Homologues: Orthologues: macaque NBPF6 (82% identical). Paralogues in human: NBPF6 (99% identical), NBPF12 (47% identical), NBPF19 (47% identical), NBPF14 (47% identical), NBPF20 (47% identical), NBPF8 (47% identical), NBPF10 (46% identical), NBPF26 (46% identical), NBPF9 (46% identical), NBPF3 (45% identical), NBPF15 (43% identical), NBPF11 (43% identical), and 1 more.
Diseases named in the same sentence as NBPF4 in open-access papers:
NBPF4 is named in the same sentence as 2 diseases in open-access papers, as found by Europe PMC text mining. Sharing a sentence is not in itself a finding about the gene and the disease.
NBPF4 shares sentences with these, for which no sentence is quoted: colorectal cancer (2 papers); neurodegenerative disease (1).